CD4 (CD4 molecule)
Diseases named in the same sentence as CD4 in open-access papers (continued):
Sharing a sentence is not in itself a finding about the gene and the disease.
tumor (continued). "Ratios of CD8:tumor cells and CD4:tumor cells in the undepleted samples were 5.45:1 and 8.04:1 respectively." (PMID 28938530, 2017). "Kreiter and coworkers previously shown that the M30 CD4+ T cell epitope completely inhibited tumor growth using a mouse model similar to the one tested in this study." (PMID 29164053, 2017). "While it is not clear why these differences exist between M3-9-M and EMT6 tumors, they offer a potential explanation for the opposing effect of CD4+ T-cell depletion on LCL161 + VSVΔM51-induced tumor regression in these two model systems." (PMID 28839138, 2017). "Combined, these data across several CD4+ tumor cells lines demonstrate that CD4CAR NK-92 cells potently target CD4+ leukemic cells, in a specific and reliable manner." (PMID 29348865, 2017). "Unfortunately, natural tumour‐specific CD4+ T cells occur in low frequency, express relatively low‐affinity T cell receptors (TCRs) and show poor reactivity towards cognate antigen." (PMID 27324616, 2017). "In a model for metastatic breast cancer, tumor-specific CD4+ T cells create a metastatic niche in bone by inducing osteolytic bone disease and subsequent release of growth factors through RANKL mediated mechanisms." (PMID 29037250, 2017). "Clinical observations further confirmed this evidence: breast cancer patients having cells positive for the tumour marker cytokeratin in the bone marrow showed a higher proportion of CD4+ and CD8+ memory T cells compared with healthy subjects." (PMID 28404796, 2017). "CD4+ regulatory T cells (Tregs) and myeloid-derived suppressor cells (MDSCs) are two of the major cell types that can promote tumor development and progression by suppressing effective antitumor immunity." (PMID 29312597, 2017). "CD4+ tumor-infiltrating lymphocytes (TILs) in melanoma produce TNF, which inhibits cytotoxic CD8+ T-cell responses." (PMID 29273790, 2017). "CD3+CD8− cells (presumably composed of CD4+ and γδ T cells) constituted 49 and 47% of the T-cell infiltrate in primary tumours and metastases, while this proportion was observed lower (36%) but without statistical significance (p = 0.73) in local relapses." (PMID 27853827, 2017). "The increase of tumor-reactive cells was observed in both the CD4+ T cell and/or the CD8+ T cell populations." (PMID 28401257, 2017). "In a mouse model of tumor vaccination, recombinant IL-7 boosted CD4 T cell function and overcame the inhibitory network imposed by the suppressive tumor microenvironment." (PMID 29272267, 2017). "Antigen-responsive CD4 T cells are believed to play a significant role in tumor-cell recognition and development of autoimmune diseases." (PMID 28314956, 2017). "The CD4-mediated cytotoxicity is sustained by literature data, suggesting tumor-specific CD4 T cells contribute to B16F10 elimination." (PMID 28974950, 2017). "After pneumonectomy for isolated tumours, histologically normal human lung tissue far from the tumours contains both CD4 and CD8 cells with diverse T cell receptors (TCR) that express CD69, produce TNFα and IFNγ and proliferate in response to influenza virus." (PMID 28475122, 2017). "Our data shows that PBT stimulates an anti-tumor immune effect that is T-cell dependent since the anti-tumor effect of PBT was lost in mice where CD4+ and CD8+ T cells were antibody-depleted." (PMID 29137411, 2017). "This subset of CD4+FOXP3+ cells express RORyt and are known to mediate pathogenic pro-tumorigenic effects in human tumours such as colorectal cancer." (PMID 28125014, 2017). "Recent studies have indicated that the balance between different CD4+ Th subsets (Th1, Th2, Th17, and Treg) is important in anti-tumor immunity, and perhaps, in the process of tumor progression." (PMID 29299026, 2017). "Our results showed that only one-third of all TILs are located in the intratumoral space while two-thirds of them (presumably CD4+ T cells, including Tregs) surrounding the tumor vessels." (PMID 29163521, 2017).
tumor (continued). "T lymphocytes were extracted from murine spleens, and CD4 and CD8a were identified as the biomarkers of activated cells participating in the anti-tumor immune response." (PMID 28720900, 2017). "The fraction βxy/(k + x) is the proliferation of CD4+ T cells through interactions with tumor cells, and αxy/(b + x) denotes the production of antitumor cytokines secreted by CD4+ T cells." (PMID 29250133, 2017). "The logic is that CD4+ T cells comprise a significant proportion of tumor infiltrating lymphocytes, and it is well-recognized that tumor antigen-specific CD4+ T cells play a significant role in tumor immunology." (PMID 28742882, 2017). "Secondly, while in antitumor reaction of the immune system, the CD8+ and CD4+ T-lymphocyte interaction among each other can induce tumor cell apoptosis, which can improve the survival of CRC patients for the chemotherapy efficacy." (PMID 28404961, 2017). "Analyzing data from a single slide, the Pearson correlation coefficients of cell type densities outside and inside tumor regions were highest for CD4 + T-cells (r = 0.8), CD8 + T-cells (r = 0.68) or CD68+ macrophages (r = 0.79)." (PMID 28923066, 2017). "In conclusion, we report that polyfunctional cytotoxic anti‐tumour CD4+ T cells can be generated through the transfer of enhanced affinity TCRs specific for HLA‐I‐restricted tumour antigens." (PMID 27324616, 2017). "We administer either l1 or l2 or both to the tumor site, where l1 represents the implementation of CD4+ T cells and l2 indicates the implementation of IL-4." (PMID 29250133, 2017). "A subpopulation of CD4+ T cells can be influenced by TGFβ stimulation and then be differentiated into interleukin 17 (IL-17)-secreting CD4+ T cells (known as Th17) that acquired additional immune-suppressive (that is, tumor-promoting) function." (PMID 28753978, 2017). "Flow cytometry showed that the majority of CD4+ tumor-infiltrating lymphocytes (TILs) in M3-9-M tumors have an activated phenotype (CD4+CD25+Foxp3−)." (PMID 28839138, 2017). "This seemingly paradox prompted us to examine the pro-inflammatory response mediated by CD4+ T cells with SHP2 deficiency and its possible outcome in anti-tumor immunity." (PMID 27935860, 2017). "It is capable of enhancing tumor Ag processing and presentation to CD4+ T cells which aids in the recognition of the tumor cells by the immune system and providing lasting immunity to malignant tumors." (PMID 29399381, 2017). "In conjunction with PBMC, the CD3xPDL1 BiTE facilitates the specific lysis of PDL1+ tumor cells by activating both CD4+ and CD8+ cytotoxic T cells and NKT cells." (PMID 28938530, 2017). "CD4+ T-cells are important for activating a range of tumour-reactive immune cells including CD8+ T-cells and B-cells." (PMID 28817839, 2017). "The results showed that the LDHA 3’UTR increased the number of tumor-infiltrating macrophages and Tregs and reduced the number of CD4+ cells and CD8+ cells." (PMID 28915924, 2017). "In the current study, we employed two types of T cells, tumor-specific CD4+ T cells or CD19-CAR T cells, for adoptive transfer following CTX-mediated host-conditioning." (PMID 29340102, 2017). "Significant differences in the CD4+/CD39+ T-cell population were detected in tumor tissue (28.8 ± 17.1% of T cells) compared to PBMC HNSCC (8.9 ± 10.2%, p < 0.0001), but not compared to non-cancerous mucosa (19.7 ± 18.4%)." (PMID 28574843, 2017). "CD4+ T-cells expressing FoxP3 are indicative of regulatory T cells (Tregs) which are thought to promote tumor progression by suppressing antitumor immunity in the tumor microenvironment." (PMID 28923104, 2017). "We found that the DTA-1 treatment only minimally affected the TCR diversity and overall frequency of dominant tumor--reactive CD4+Foxp3−Teff clones (Teffs)." (PMID 28638937, 2017).
tumor (continued). "According to analysis of clinical samples and experimental studies, we found that the accumulated CD4+ cells in the stroma are the main source of IL-6, which in turn triggers the tumor cell EMT that induces the mesenchymal phenotype of tumor cells." (PMID 28846080, 2017). "As well as in other solid tumors, forkhead box P3 (FOXP3) + T-regs, a subset of CD4+ T cells specialized in the suppression of the host immune system against self antigens, promotes tumor development inducing a state of severe immune-suppression in HCC." (PMID 28420805, 2017). "Podoplanin-expressed lymph node stromal cells enhance tumor growth in vivo by eliminating CD4+ tumor-infiltrating lymphocytes that limit the efficiency of tumor immunotherapy." (PMID 28674748, 2017). "To identify tumor-specific clones that recognize Ep63K neo-antigen or native B16 antigens, we immortalized CD4+Teffs and Tregs sorted from tumor mass or tumor draining lymph nodes of both untreated and DTA-1 treated TCRmini mice." (PMID 28638937, 2017). "Another important check point molecule, CTLA4 is broadly engaged in tumor immune evasion through the down-regulation of CD4+ T effector (Teff) cells and the enhancement of Treg cell activity." (PMID 28878676, 2017). "Next, we assessed that the diversity of TCR repertoires of tumor-specific CD4+Teffs and Tregs in pLN, dLN, and tumor in treated and untreated mice was assessed by counting numbers of tumor-reactive CD4+Teffs and Tregs clones." (PMID 28638937, 2017). "Utilizing those schedules, DTA-1 addition enhanced tumor protection/regression and those effects were attributed to enhanced costimulation of CD4+FoxP3- and CD8+ effector T cells with the simultaneous inhibition of Treg suppression." (PMID 29088720, 2017). "The combination of the anti-PD-L1 blocking mAb with the cell-depleting anti-CD4 mAb had also cooperative anti-tumor effects." (PMID 29070883, 2017). "GBM tumors were enriched with PD-1+TIM-3+CD4+ effector cells; the percentage of which correlated with tumor grade." (PMID 28880903, 2017). "The deviation towards ex-Th17 Treg cells (IL17AnegFoxp3+ of eYFP+) is promoted under Treg-driving conditions, that is, TGF-β and when the CD4+ T cells are cultured in tumour cell conditioned medium." (PMID 28290453, 2017). "Given the known role of ICOS in the development of follicular helper T cells, tumour-infiltrating lymphocytes (TILs) from the virus-treated tumours were characterized for the expression of Tfh lineage-specific markers (CD4+FoxP3−CXCR5+PD-1+ICOS+)." (PMID 28194010, 2017). "It is conceivable that in the setting of ACT, tumor-specific CD4+ T cells would receive antigenic stimulation while being exposed to increased levels of endogenous IL-7." (PMID 28939858, 2017). "CD8+ T lymphocytes mediate potent immune responses against tumor, but the role of human CD4+ T cell subsets in cancer immunotherapy remains ill-defined." (PMID 29213079, 2017). "Here, we show that co-expansion of CD4+CD25hiFoxP3+ T cells and/or tumor cell produced IDO and galectin-3 during MLTC have a negative impact on the activation and expansion of tumor-specific T cells, and we describe different manners to circumvent this." (PMID 28401257, 2017). "To analyze the complexity of TCR repertoire of lymph node and tumor-infiltrating CD4+Teffs and Tregs and to determine a proportion of common TCRs in treated and non-treated mice, we compared TCRs from these functionally different T cells." (PMID 28638937, 2017). "In particular, we combined a B cell epitope to a CD4+ T cell epitope and we showed that, together, the two epitopes completely abrogate tumor growth." (PMID 29164053, 2017). "A flow cytometry analysis of tumour infiltrating T-cells revealed a statistically insignificant trend in the proportion of CD4+ and CD8+ T-cells between the vehicle and IgG control treatment group and all single and double-treated mice." (PMID 28198370, 2017).
tumor (continued). "Given that IL-7Rα expression is regulated by both TCR and IL-7 signaling, we went on to delineate the impact of TCR and/or IL-7 signaling on the IL-7 responsiveness of tumor-specific CD4+ T cells as well as bystander T cells." (PMID 28939858, 2017). "These mice were injected with α-CD8 Ab on days 10, 11, 12, or α-CD4 Ab injection at days 10, 15, 20 post tumour cell inoculations." (PMID 28345650, 2017). "Analysis of virus-injected tumours revealed enhanced tumour infiltration with CD4+FoxP3− and CD8+ cells in the animals treated with NDV-ICOSL, which reached statistical significance over the NDV-WT group in the distant tumours." (PMID 28194010, 2017). "Caveats of systemic IL-2 administration include treatment-associated toxicity, its rapid clearance in vivo and IL-2 pro-tumor effects through the concurrent activation of CD4+ regulatory T cells." (PMID 29181007, 2017). "Most F4/80+ or CD4+ cells were co-stained with anti-IL-25, suggesting that these cells are the major source of IL-25 in the tumor." (PMID 27909985, 2017). "NSG mice transplanted with cells from a primary Gzmb-HBZ tumor had detectable CD4 and CD8 T cells in the spleen." (PMID 29050201, 2017). "CD8+ CTLs were essential anti-tumor effector cells in mice treated with the anti-CD4/anti-PD-1 mAb combination as CD8+ T cell depletion in vivo completely abrogated the effect of the combined immunotherapy." (PMID 29070883, 2017). "CD8+ T cells are more effective in killing cancer cells, but the helper function of CD4+ Th1 cells improves the efficacy of tumor-reactive CD8+ T cells." (PMID 28542574, 2017). "In this analysis of 105 patients with resected stage I pulmonary squamous cell carcinoma, tumor PD-L1 expression and increased CD4+ T cell infiltrations in tumor stroma were found to be independent predictors of better overall survival." (PMID 28514966, 2017). "Next, we evaluated the phenotypes of ex vivo—expanded CD4 T+ cells that were transferred into lymphopenic tumor-bearing mice." (PMID 28854279, 2017). "This is illustrated by the complete tumor eradication of melanoma after transfer of NY-ESO-1-specific CD4+ T cells and genetically engineered NY-ESO-1 specific T cells." (PMID 28959257, 2017). "Current evidence has suggested that CD8-positive cytotoxic lymphocytes rely on CD4-positive T cells and can moderate the destruction of tumor cells." (PMID 28817603, 2017). "As CD103+ DCs have been associated with the priming of robust anti-tumour CD8+ T cell responses, we analysed the dLN-resident T cell compartment with respect to the presence of CD8+ vs. CD4+ T cells." (PMID 28924177, 2017). "(A) Tumour cells have developed several mechanisms that directly or indirectly block the activity of effector antitumour CD4+ and CD8+ T cells dampening local tumour-infiltrating immune responses." (PMID 28758114, 2017). "Mice infected with attenuated anti-tumour S. Typhimurium have similarly been noted to have decreased numbers of CD4+CD25+ cells." (PMID 28584281, 2017). "Treatment with PBT significantly decreased the populations of Gr1+CD11b+ myeloid derived suppresser cells (MDSC) and CD25+CD4+ T regulatory cells (Tregs), major immunosuppressive cell types found in many different tumor types." (PMID 29137411, 2017). "C57BL/6 mice injected intradermally in the ear with B16F10 tumour cells developed solid tumours with steady increases in both absolute numbers and ratios of Foxp3+CD4+ Treg cell population." (PMID 28504276, 2017). "Immunofluorescence and FACS analyses, suggested the presence of more abundant CD4+CD25−Lag3+ Tr-1 cells in NXS2 than in Neuro2a tumors, while CD4+CD25+ Treg cell counts were similar in both tumor types." (PMID 29070883, 2017). "Among CD4+ T cells, both CD4+ Teffs (CD4+ FoxP3−) and Tregs (CD4+ FoxP3+) infiltrated the tumour and uninvolved pancreatic tissue in equal relative proportions in both tumours and uninvolved tissue." (PMID 28447602, 2017).
tumor (continued). "We show that antibiotics administration had detrimental effect on the efficacy of ACT using tumor-specific CD4+ T cells." (PMID 29340102, 2017). "When we conducted the miRNA array analysis against the normal CD4+ T-cells that were exposed to vorinostat or panobinostat, we detected significantly lower miRNA expression changes than those of the tumor cells." (PMID 27935859, 2017). "On the other hand, lymphocytes, usually CD4+ helper T and natural killers cells form the major component of the cell-mediated immune response to tumor infiltration and can attack tumor cells and eliminate nascent cancer cells." (PMID 28195186, 2017). "Let x, y, and z denote tumor cells, CD4+ T cells, and antitumor cytokine (IL-4 or any antitumor cytokine produced by Th2), respectively." (PMID 29250133, 2017). "For further confirmation, we sorted tumor macrophages (CD45+CD11b+F4/80+Gr-1-), tumor-infiltrating CD4+ (CD45+CD4+CD11b-), and CD45- cells, and then examined the mRNA level of IL-17RB in these cells." (PMID 27909985, 2017). "Tumor regression was dependent on Teffs as depletion of both CD4 and CD8 T cells completely abrogated any survival benefit." (PMID 28250921, 2017). "The percentage of effector CD4+ T cells (Foxp3−CD4+) in tumour infiltrating CD45+ cells was significantly smaller in the dual treatment group on day 2, but higher than other groups by day 5 (P=0.05)." (PMID 28345650, 2017). "The results indicate that CTX preconditioning is a prerequisite for donor CD4+ T cells to acquire IL-7 responsiveness, which correlates with the functional status of tumor-reactive CD4+ T cells." (PMID 28939858, 2017). "Meanwhile, the spleens of subcutaneous tumor‐bearing mice had an 81% decrease in CD4+ and CD8+ T‐cells compared to controls (respectively)." (PMID 28250928, 2017). "At the challenge site, a dramatic decrease in tumor progression was observed and was dependent on tumor-infiltrating CD4+ and CD8+ T lymphocytes." (PMID 29050360, 2017). "Proliferative activity of both CD4 and CD8 T cells from tumour-draining lymph nodes was higher in TLR-deficient mice compared with WT controls." (PMID 28300057, 2017). "Therapeutic efficacy is associated with increases in the systemic level of tumor-specific CD8+ T cells, and an increased ratio of intratumoral CD8+ T cells to CD4+ Tregs." (PMID 29129918, 2017). "So far we have demonstrated that DTX‐mediated Treg depletion in tumor bearing BALB/c FoxP3.dtr mice is associated with significant increases in CD8 and CD4 T cell activation and an overall survival benefit, compared to untreated controls." (PMID 28250921, 2017). "CD4+ effector T cells that were primed in TDLNs and stimulated with IL-7 and IL-23 inhibited tumor progression more strongly than those stimulated with IL-2 and IL-7 when they were transferred into lymphopenic tumor-bearing mice." (PMID 28854279, 2017). "In the complex set of cellular interactions within the FL microenvironment, tumor-infiltrating CD4+ T cells display overlapping functions with critical roles." (PMID 29340116, 2017). "It is noteworthy that transfer of either primed CD4+ T cells, B cells, or sera on the day of tumor inoculation provides superior tumor immunity when compared to active immunization on the day when tumors become palpable." (PMID 28428886, 2017). "While the role of CD4 CTL in protection against tumor formation requires more directed study, the use of immunotherapy and vaccination to induce cytotoxic CD4 responses against tumor antigens is gaining interest, as discussed later in the review." (PMID 28167943, 2017). "Here, we show that the combination of the anti-CD4 depleting mAb with either PD-1 or PD-L1-blocking mAbs has anti-tumor synergistic effects, leading to 100% and 90% cure rates, in the Neuro2a model, respectively." (PMID 29070883, 2017). "Accumulating evidence suggests that CD4+FoxP3+ Tregs are expanded in various cancers including breast and suppress anti-tumor immunity." (PMID 28388539, 2017).